PROX1 (prospero homeobox 1)
Description:
Transcription factor involved in developmental processes such as cell fate determination, gene transcriptional regulation and progenitor cell regulation in a number of organs. Plays a critical role in embryonic development and functions as a key regulatory protein in neurogenesis and the development of the heart, eye lens, liver, pancreas and the lymphatic system. Involved in the regulation of the circadian rhythm. Represses: transcription of the retinoid-related orphan receptor RORG, transcriptional activator activity of RORA and RORG and the expression of RORA/G-target genes including core clock components: BMAL1, NPAS2 and CRY1 and metabolic genes: AVPR1A and ELOVL3.
Tractability: PROTAC: UniProt records ubiquitination sites on it; its protein half-life has been measured.
Safety:
Unwanted effects reported when the protein is acted on. In parentheses: how it was acted on, where the effect was seen, and who reports it.
increase in fasting glucose (source: ClinPGx)
Gene: Protein-coding gene on chromosome 1 (213,982,711 to 214,041,510, forward strand). Ensembl gene ENSG00000117707.
Subcellular location: Nucleus
Subcellular location (Human Protein Atlas): Nucleoplasm; Cytosol
Gene Ontology:
Molecular function: DNA binding; DNA binding domain binding; DNA-binding transcription activator activity, RNA polymerase II-specific; DNA-binding transcription repressor activity, RNA polymerase II-specific; LBD domain binding; nuclear receptor binding; protein binding; sequence-specific double-stranded DNA binding; transcription cis-regulatory region binding; DNA-binding transcription factor activity, RNA polymerase II-specific; RNA polymerase II cis-regulatory region sequence-specific DNA binding; sequence-specific DNA binding
Biological process: brain development; embryonic retina morphogenesis in camera-type eye; hepatocyte differentiation; kidney development; lens development in camera-type eye; lens fiber cell morphogenesis; liver development; lung development; lymphangiogenesis; lymphatic endothelial cell differentiation; lymphatic endothelial cell fate commitment; negative regulation of bile acid biosynthetic process; negative regulation of cell population proliferation; negative regulation of DNA-templated transcription; negative regulation of transcription by RNA polymerase II; negative regulation of viral genome replication; pancreas development; positive regulation of cell population proliferation; positive regulation of endothelial cell migration; positive regulation of endothelial cell proliferation; positive regulation of transcription by RNA polymerase II; positive regulation of vascular endothelial growth factor signaling pathway; regulation of circadian rhythm; regulation of gene expression; aorta smooth muscle tissue morphogenesis; and 30 more
Cellular component: cytoplasm; cytosol; nucleoplasm; nucleus; chromatin
Genetic constraint (gnomAD): Loss-of-function variants: 7 observed, 59.28 expected, observed/expected ratio (o/e) 0.12, 90% interval 0.066 to 0.22. The upper end of that interval is the gene's LOEUF score, 0.22, which puts it in group 1 of 6, group 1 being the genes least tolerant of losing a copy. Missense variants: 675 observed, 974.07 expected, observed/expected ratio (o/e) 0.69, 90% interval 0.65 to 0.74. Synonymous variants: 350 observed, 378.53 expected, observed/expected ratio (o/e) 0.92, 90% interval 0.85 to 1.01.
Gene-disease validity (ClinGen):
ClinGen rates the evidence that PROX1 causes each of these diseases.
congenital heart disease (autosomal dominant): Disputed. A heart disease that is present at birth.
Homologues: Orthologues: chimpanzee PROX1 (100% identical), macaque PROX1 (100% identical), dog PROX1 (99% identical), rabbit PROX1 (99% identical), pig PROX1 (99% identical), guinea pig PROX1 (99% identical), mouse Prox1 (98% identical), tropical clawed frog prox1 (88% identical), zebrafish prox1a (82% identical), rat Prox1 (82% identical), Drosophila melanogaster pros (31% identical), Caenorhabditis elegans pros-1 (20% identical). Paralogues in human: PROX2 (28% identical).
Diseases named in the same sentence as PROX1 in open-access papers:
PROX1 is named in the same sentence as 156 diseases in open-access papers, as found by Europe PMC text mining. Sharing a sentence is not in itself a finding about the gene and the disease. The quoted sentences say what the papers report.
breast carcinoma (34 papers, 2008 to 2025). "Specifically, Prox1 dysregulation is linked to breast cancer progression and metastasis and glioblastoma invasion, while Zmiz1 is associated with breast cancer and prostate cancer." (PMID 38718095, 2024). "Consistently, a recently reported Genome-Wide Association Study (GWAS) found a susceptibility locus over Prox1 regulatory sequences that significantly increases the risk for breast cancer in children that received radiotherapy." (PMID 37508533, 2023). "In particular, we showed that breast tumors from human patients exhibited reduced levels of Prox1 expression, while high expression levels of Prox1 were associated with a favorable prognosis in breast cancer patients." (PMID 37508533, 2023). "Others have confirmed that deletion, mutation, and hyper-methylation of the Prox1 gene can lead to the occurrence of biliary tumors, esophagus cancer, and breast cancer." (PMID 34183992, 2021). "This action may also explain the existence of a breast cancer susceptibility locus over the Prox1 gene regulatory elements in radiotherapy-treated children." (PMID 37508533, 2023). "Although these data raise the hypothesis that Prox1 may be negatively associated with tumorigenesis, its role and mechanism of action in breast cancer remain elusive." (PMID 37508533, 2023). "The levels of Interleukin 24 (IL-24), a cytokine that inhibits tumor progression, and its receptor, the IL-24 receptor (IL-24R), are found to be reduced in breast cancer samples and are associated with increased levels of lymph-specific markers, such as podoplanin, PROX1, and LYVE-1." (PMID 35885529, 2022). "Two genes, Asap1 and Prox1, respectively implicated in breast cancer metastasis and progenitor cell function in other systems, were selected for further analysis as their roles in the normal mammary gland were unknown." (PMID 25879659, 2015). "Therefore, it was concluded that PROX1 could serve as a substantial therapeutic target as well as an important diagnostic marker for patients with breast cancer." (PMID 40660330, 2025). "Thus, PROX1 could act as an important diagnostic marker and also significant therapeutic target for breast cancer patients." (PMID 35342346, 2022). "In some studies, PROX1 operates as a tumor suppressor, with the reduced migration and invasion of breast cancer cells." (PMID 39941895, 2025). "To further investigate the possible involvement of Prox1 in the metabolic properties of breast cancer cells, we measured the glucose uptake and lactate secretion of Prox1 over-expressing breast cancer cells." (PMID 37508533, 2023). "Here, we showed that Prox1 exhibits a tumor-inhibiting function in breast cancer by directly repressing the c-Myc gene expression at the transcriptional level." (PMID 37508533, 2023). "For example, in breast cancer, PROX1 has been shown to stimulate the Wnt/β-catenin signaling pathway, thereby enhancing EMT and promoting distant metastasis." (PMID 37345154, 2023). "Collectively, our observations suggest that Prox1 suppresses the c-Myc gene expression to inhibit the Warburg effect, proliferation, migration, and tumor growth in breast cancer cells." (PMID 37508533, 2023). "In particular, we revealed a critical role for Prox1 in inhibiting breast cancer through the negative regulation of c-Myc at the transcriptional level." (PMID 37508533, 2023). "Using different breast cancer cell lines, we showed that Prox1 reverses the Warburg effect by repressing glucose uptake and lactate secretion." (PMID 37508533, 2023). "Most importantly, Prox1 over-expression reverses the malignant phenotype of breast cancer cells in heterotopic and orthotopic xenograft models by suppressing proliferation, migration, and tumor growth." (PMID 37508533, 2023). "In breast cancer, PROX1 activates the WNT/β-catenin signaling pathway in conjunction with hnRNPK, leading to cancer cell invasion and metastasis." (PMID 37685269, 2023).
breast carcinoma (continued). "By using the Oncomine database to analyze TCGA data from breast cancer patients, we observed a strong reduction in Prox1 gene expression in various subtypes of invasive breast carcinoma as compared to healthy tissue." (PMID 37508533, 2023). "Conclusively, in this study, we revealed a key role for Prox1 in inhibiting breast cancer progression through the negative regulation of c-Myc." (PMID 37508533, 2023). "To evaluate the role of Prox1 in migration and invasion of breast cancer cells, we performed wound healing and Transwell assays." (PMID 37508533, 2023). "Specifically, we tested the ability of Prox1 to affect the numbers of BrdU+ breast cancer cells in typical BrdU incorporation experiments following a 2 h pulse (before to fixation)." (PMID 37508533, 2023). "It has also been previously shown that Prox1 expression is repressed in breast cancer cells due to epigenetic silencing." (PMID 37508533, 2023). "Through this action, Prox1 inhibited the proliferation and migration of breast cancer cells, as well as tumor growth in heterotopic and orthotopic xenograft models." (PMID 37508533, 2023). "Via this action, Prox1 strongly suppresses human breast cancer cell growth, Warburg effect and invasion, in vitro and in vivo, in a non-apoptotic way." (PMID 37508533, 2023). "Our study identified the transcription factor Prox1 as a negative regulator of the Warburg effect in breast cancer cells." (PMID 37508533, 2023). "In agreement with such a role, it was previously reported that Prox1 expression is epigenetically repressed in breast cancer cells by DNA methylation." (PMID 37508533, 2023). "To this end, here, we identified Prox1 as a negative regulator of proliferation and tumor-related metabolism in breast cancer." (PMID 37508533, 2023). "We investigated the mRNA expression of hnRNPK in breast cancer cell lines with altered PROX1 expression." (PMID 35342346, 2022). "We reported that PROX1 promote metastasis and invasion of breast cancer through the WNT pathway by interacting with hnRNPK which can facilitate β-catenin nuclear translocation." (PMID 35342346, 2022). "The overexpression of PROX1 gained stronger invasion and migration ability, while knockdown of PROX1 weakened the invasion and migration ability in breast cancer cells." (PMID 35342346, 2022). "In this study, we found that PROX1 was frequently up-regulated in breast cancer patients and acted like oncogene by inducing EMT in vitro and in vivo." (PMID 35342346, 2022). "GSE data analysis further showed that the expression of PROX1 was significantly increased in breast cancer patients with disease recurrence and docetaxel resistance." (PMID 35342346, 2022). "To elucidate role of PROX1 in breast cancer metastasis, we screened the mRNA and protein level of PROX1 in different cell lines." (PMID 35342346, 2022). "D2-40, LYVE-1, and PROX-1 are recognized LEC markers in human breast cancer, among which D2-40 has the best performance in lymphangiogenesis assessment from the current study." (PMID 35054174, 2021). "In contrast, PROX1 mRNA expression was markedly decreased in lymphoid malignancies and breast carcinoma tissues." (PMID 24797520, 2014). "Prox1 acts as a tumor suppressor in hematologic malignancies, esophageal cancer, hepatoma, pancreatic cancer, breast cancer, and carcinomas of the biliary system." (PMID 24647631, 2014). "On the other hand, Prox1 acts as a tumor suppressor in hematologic malignancies, esophageal cancer, hepatoma, pancreatic cancer, breast cancer, and carcinomas of the biliary system." (PMID 24647631, 2014). "Thus, clinical data from these databases suggest a correlation between low expression levels of Prox1 and breast cancer progression." (PMID 37508533, 2023). "Thus, we concluded that the inhibitory action of Prox1 on c-Myc gene expression mediates the tumor-suppressing function of Prox1 in breast cancer cells." (PMID 37508533, 2023).
breast carcinoma (continued). "To determine whether the observed correlation between Prox1 expression and favorable prognosis in patients has a functional significance, we analyzed proliferation and apoptosis in human breast cancer cell lines as a model system." (PMID 37508533, 2023). "To further investigate the c-Myc/Prox1 interaction, we assessed whether c-Myc over-expression from an artificial promoter, lacking the Prox1 binding sites of the endogenous c-Myc gene, could rescue the anti-proliferative effect of Prox1 on breast cancer cells." (PMID 37508533, 2023). "Subsequently, we examined whether Prox1 was able to inhibit the proliferation of breast cancer cells from this mouse model." (PMID 37508533, 2023). "Taken together, these data support a hypothesis about the tumor-suppressing role of Prox1 in breast cancer progression." (PMID 37508533, 2023). "Moreover, our mRNA expression analysis in breast cancer cells suggests that Prox1 represses c-Myc expression." (PMID 37508533, 2023). "Therefore, this study predominantly focuses on exploring the role of PROX1 in breast cancer in vitro and in vivo." (PMID 35342346, 2022). "However, another study found a reduced expression of PROX1 in breast cancer tissues and in brain metastases from breast cancer patients, compared to normal breast tissue." (PMID 35885529, 2022). "This study takes the new evidence to support PROX1 as an oncogene in breast cancer." (PMID 35342346, 2022). "Furthermore, PROX1 can interact with hnRNPK to activate WNT/β-catenin signaling in breast cancer cells." (PMID 35342346, 2022). "Result showed that up to 15% of breast cancer patients were PROX1 amplified." (PMID 35342346, 2022). "Besides, immunohistochemical staining was used to analyze the expression of PROX1 in 74 pairs of breast cancer and normal tissues." (PMID 35342346, 2022). "Five studies exist exploring the role of PROX1 in the development and spread of breast cancer." (PMID 35885529, 2022). "Additionally, PROX1 protein expression was significantly reduced in brain metastases and breast cancer tissues." (PMID 35885529, 2022). "Assuming that in breast cancer, PROX1 acts as a tumor-suppressive gene, the demethylation of PROX1 and reactivation could represent a possible therapeutic strategy." (PMID 35885529, 2022). "Collectively, these data confirmed that PROX1 contributes breast cancer metastases in vitro." (PMID 35342346, 2022). "Meanwhile, PROX1 can promote breast cancer invasion and metastasis in vitro and in vivo." (PMID 35342346, 2022). "LncRNA LINC00968 inhibits miR‐423‐5p expression in a concentration‐dependent manner and mediates upregulation of prospero homeobox 1 (PROX1) expression to inhibit breast cancer progression, such as cell proliferation, migration, and tube‐forming ability as well as tumor growth." (PMID 33174687, 2020). "Moreover, PROX1 ectopic expression reduced the MMP14-dependent 3D invasiveness of breast cancer cells and angiogenic sprouting of blood endothelial cells in conjunction with MMP14 suppression." (PMID 29934628, 2018). "In hematological malignancies and in breast cancer PROX1 expression has been shown to be decreased." (PMID 27411302, 2016). "Four transcription factors (Bcl11a, Grhl3, Prox1, Sox11) activated in Brca1-/- mouse tumors and basal-like human breast cancers across multiple datasets were chosen for validation studies, and all were confirmed to be embryonic-enriched and highly expressed by some tumors." (PMID 23506684, 2013). "Furthermore, based on our experimental observations, we cannot exclude additional regulatory actions of Prox1 on other genes or pathways that may contribute to its anti-tumorigenic role in breast cancer." (PMID 37508533, 2023). "Moreover, we unraveled a previously unknown action of Prox1 in suppressing the Warburg effect on breast cancer cells that may also apply in other tissues, where Prox1 exhibits tumor-suppressive roles." (PMID 37508533, 2023).